BCOR (BCL6 corepressor)
Diseases named in the same sentence as BCOR in open-access papers (continued):
Sharing a sentence is not in itself a finding about the gene and the disease.
medulloblastoma (11 papers, 2013 to 2025). A malignant, invasive embryonal neoplasm arising from the cerebellum. "In contrast to the BCOR deletion or truncating mutations frequently seen in other tumors such as medulloblastoma and myeloid malignancies, BCOR levels are upregulated in CNS tumors with BCOR-ITD alterations." (PMID 33920124, 2021). "In CNS tumors, loss of function BCOR mutations (e.g., nonsense, frameshift, splice sites and deletions) have been described in medulloblastoma, high-grade pediatric gliomas and astroblastomas." (PMID 32493417, 2020). "BCOR was significantly mutated in medulloblastoma such as other nuclear co-repressor (N-CoR) complex genes." (PMID 23577124, 2013). "In addition, we analyzed the changes of proteins (APC, CTNNB1, DDX3X, PTEN, BCOR) associated with medulloblastomas in CB at the four developmental stages." (PMID 37400444, 2023). "Furthermore, BCOR functions as a tumor suppressor within the PRC1.1 complex, and its inactivation accelerates SHH-driven tumorigenesis in medulloblastoma models." (PMID 41419593, 2025).
clear cell sarcoma of the kidney (10 papers, 2018 to 2025). "In the kidney, the identification of a BCOR ITD is diagnostic for clear cell sarcoma of the kidney." (PMID 37686670, 2023). "Strikingly, a subgroup of URCS tumors with BCOR alterations contain a mutant BCOR form with an internal tandem duplication of a region towards the C-terminal end, a mutation that is also found in a range of other tumor types like clear cell sarcoma of the kidney and others." (PMID 38611033, 2024). "Intragenic tandem duplication is a well-known mechanism to activate oncogenes, for example, FLT3 internal tandem duplication (ITD) in acute myeloid leukemia and BCOR ITD in clear cell sarcoma of kidney (CCSK)." (PMID 32490123, 2020). "BCOR-ITD and YWHAE-rearranged tumors define an infantile SRCS subset with truncal/abdominopelvic predilection, aggressive behavior, and characteristic immunophenotypes (BCOR, cyclin D1, SATB2), overlapping morphologically with clear cell sarcoma of the kidney." (PMID 41514642, 2025). "Aberrant BCOR (BCL6 corepressor) expression has been found in a variety of tumor types, including clear cell sarcoma of the kidney, endometrial sarcoma, rhabdomyosarcoma, and central nervous system and myeloid tumors." (PMID 36765856, 2023). "Tumor types included additional cases of CMN (n = 63), IFS (n = 26), Wilms tumor (n = 208), clear cell sarcoma of the kidney without BCOR rearrangements (n = 20), malignant rhabdoid tumor (n = 3), and nephroblastomatosis (n = 12)." (PMID 29915264, 2018). "In addition, it has the advantage of being positive in the wider family of tumors which share BCOR overexpression due to BCOR internal tandem duplications (ITD) or other gene fusions; examples include clear cell sarcoma of kidney and primitive myxoid mesenchymal tumor of infancy." (PMID 33921435, 2021).
Myelodysplasia (10 papers, 2022 to 2025). Clonal hematopoietic stem cell disorders characterized by dysplasia (ineffective production) in one or more hematopoietic cell lineages, leading to anemia and cytopenia. "Seventy-nine patients, or 45% of all re-classified patients, were moved from ELN-2017 favorable (n = 11) or intermediate (n = 68) to ELN-2022 adverse risk based on the inclusion of additional myelodysplasia-related (MR) mutations (BCOR, EZH2, SF3B1, SRSF2, STAG2, U2AF1, ZRSR2) as poor-risk markers." (PMID 37041198, 2023). "In particular, the adverse-risk group has been expanded to include seven additional mutations: BCOR, EZH2, SF3B1, SRSF2, STAG2, U2AF1, and ZRSR2—together with ASXL1 and RUNX1 (already included in ELN 2017)—forming the “myelodysplasia-related” (MR) gene group." (PMID 41464583, 2025). "The co-occurrence of two different myelodysplasia-associated somatic variants (CUX1/ETV6 and ASXL1/BCOR) was observed in 2 patients." (PMID 41188636, 2025). "Only 5 were assigned to the adverse group because of myelodysplasia-related mutations (RUNX1, n = 2; BCOR, n = 1; SF3B1, n = 1; U2AF1, n = 1)." (PMID 37085611, 2023). "The presence of mutations in at least one gene associated with myelodysplasia (i.e., SRSF2, SF3B1, U2AF1, ZRSR2, ASXL1, EZH2, BCOR, or STAG2) was significantly more frequent in older patients." (PMID 35805006, 2022). "Eight myelodysplasia-associated somatic variants in the BCOR/BCORL1, DNMT3A, ASXL1, CUX1, and ETV6 genes were found in 7 patients (5 AA and 2 MDS-h patients, 17%); neither AA patient had evidence of myelodysplasia at the time of analysis." (PMID 41188636, 2025).
lymphoma (8 papers, 2017 to 2025). A malignant (clonal) proliferation of B- lymphocytes or T- lymphocytes which involves the lymph nodes, bone marrow and/or extranodal sites. "Within the genetic heterogeneity of CLL, disruptive mutations of the BCL6 co-repressor (BCOR) were found in up to 2% of cases and have been included among the lymphoma driver genes." (PMID 40113912, 2025). "Lymphoma patient samples were analyzed to identify missense mutations in BCOR using Sanger sequencing." (PMID 33468080, 2021). "One hundred thirty-seven lymphoma patient samples were analyzed to identify K607E mutation of the BCOR gene." (PMID 33468080, 2021). "The results indicated that K607E mutation of BCOR occurs in all tested subtypes of lymphoma with an overall frequency of 30%." (PMID 33468080, 2021). "This demonstrates that BCOR loss-of-function, either engineered or through spontaneous mutation, drives a unique and reproducible transcriptional pattern in Eμ-Myc lymphomas." (PMID 28262675, 2017). "In order to more precisely estimate the frequency of BCOR mutation in lymphoma patients, we examined genomic DNA from 47 NK/T cell lymphoma patient samples and detected two types of nonsense mutations (E197X and W289X) along with one type of missense mutation (K607E)." (PMID 33468080, 2021). "We further identified a novel K607E mutation of BCOR gene in a cohort of 137 lymphoma patients." (PMID 33468080, 2021). "Nine lymphomas with BCOR loss-of-function were IgM−/IgD−, while only one was IgM+/IgD−." (PMID 28262675, 2017). "In this study, we report for the first time the frequencies of BCOR K607E mutation in various types of TCLs and the functional role of mutant BCOR in malignant lymphoma cells." (PMID 33468080, 2021). "BCL6 Corepressor (Bcor) loss drives alterations in the B-cell compartment, promotes the transformation of CLL into aggressive lymphoma, and frequently co-occurs with mutated NOTCH1 which is a hallmark of RT, suggesting the therapeutic potential of targeting Bcor and NOTCH1 in RT." (PMID 40565027, 2025).
myeloid malignancies (8 papers, 2019 to 2026). "BCOR/BCORL1 mutations are common in myeloid tumors, such as acute myeloid tumors, and detectable mutation types include small insertions and deletions, frameshift mutations, nonsense mutations, and splice site mutations." (PMID 41262533, 2026). "Some studies have demonstrated poor prognosis in patients with myeloid tumors with BCOR/BCORL1 mutations." (PMID 41262533, 2026). "Mutated BCOR: The BCL6 corepressor (BCOR) is a tumor suppressor gene, which is dysfunctional in lymphoid and myeloid tumors." (PMID 38673842, 2024). "Carriers of BCORL1 mutation, such as PIGA and BCOR, exhibit a lower risk of progressing to secondary myeloid neoplasms, and thus, this variant could represent a marker of immune selection without being a significant driver of myeloid malignancy." (PMID 36499545, 2022). "Other co-mutations often seen in myeloid neoplasms with germline RUNX1 are in DNMT3A, FLT3, GATA2, PHF6 (PHD finger protein 6), BCOR (BCL6 Corepressor), WT1, and TET2." (PMID 35054439, 2021). "Mutational profiling revealed mutations in four genes associated with myeloid malignancies, namely, EZH2, CUX1, TET2, and BCOR." (PMID 33628448, 2021). "Mutations of BCOR at various coding sites have been frequently seen in lymphoid and myeloid malignancies but not so far in MCL." (PMID 31334109, 2019).
embryonal tumors (7 papers, 2021 to 2025). "As CNS tumors with BCOR ITD have been included in the chapter on embryonal tumors in the last WHO classification, further studies are needed to determine the cell of origin for their counterparts having BCOR(L1) fusions." (PMID 36782314, 2023).
soft tissue tumors (7 papers, 2022 to 2025). "Herein, we present the clinicopathological, immunohistochemical, and molecular profiles of seven soft tissue tumors exhibiting ZC3H7A/B::BCOR fusions." (PMID 40705064, 2025). "The better understanding of pathogenesis in soft tissue tumors combined with NGS as a diagnostic tool led to the detection of four fusions of the RGAG1 and the BCOR gene, with probably only one of these fusions being functional." (PMID 34331570, 2022).
synovial sarcoma (7 papers, 2020 to 2025). "In the current work, a primary synovial sarcoma of the kidney with unusual morphological features (extensively myxoid stroma and immunohistochemical positivity for BCOR) is described." (PMID 39000489, 2024). "eGFP-SSX-C expression in synovial sarcoma cells led to higher BCOR and H2AK119ub1 levels in a manner that correlated with eGFP reporter levels." (PMID 37735617, 2023).
brain tumor (6 papers, 2020 to 2024). "Methylation profiling showed a significant calibrated score of 0.99 in v12.5 and v12.8 versions of Heidelberger brain tumor classifier and lower calibrated score of 0.79 in v11.b4 for methylation family class “CNS tumor with BCOR alteration”." (PMID 38637838, 2024). "To investigate the role(s) of wildtype BCOR (BCOR-WT) or BCOR-ITD in controlled systems relevant to brain tumors, we introduced them into human and murine neural stem cells (hNSC and mNSC) by lentiviral transduction." (PMID 33920124, 2021). "Nevertheless, BCOR can be also expressed in other brain tumors, especially in CNS HGNET-MN1, what is visible at the RNA level in our series as well." (PMID 32650833, 2020). "Besides, five additional inputs were found after searching for alterations in BCOR, BCORL1, EP300, TRAP1, CREBBP, and L3MBTL2 in the repository of 23 published studies on neuroepithelial brain Tumors including 7207 samples of 6761 patients." (PMID 38637838, 2024).
ependymoma (6 papers, 2022 to 2024). A WHO grade II, slow growing tumor of children and young adults, usually located intraventricularly. "There is a morphological overlap between BCOR–CREBBP- and BCOR ITD/EP300-BCOR-fused CNS tumors including oligodendrocyte- or ependymoma-like morphology, microcystic changes and also focal calcifications associated with anaplastic features." (PMID 39409964, 2024). "Immunohistochemistry should be performed for EMA or podoplanin, GFAP, BCOR, and p65-RELA or L1CAM for ZFTA-RELA ependymomas." (PMID 36604386, 2023).
gastric cancer (6 papers, 2015 to 2024). A primary or metastatic malignant neoplasm involving the stomach. "EBV-GCs, one of 4 molecular subtypes of gastric cancer, had frequent BCOR mutations (3 nonsense and 1 splicing) compared with the other 3 types (15.4% vs 4.8%, P = 0.051)." (PMID 25980440, 2015). "EBV-positive gastric cancers are reported to have recurrent mutations of PIK3CA, ARID1A, and BCOR and amplifications of JAK2, PD-L1, and PD-L224." (PMID 34873204, 2021). "Some mutations have been also observed in gastric cancer patients as well as Epstein-Barr virus infection including PIK3CA, ARID1A and BCOR mutations." (PMID 33024525, 2020). "Epstein–Barr virus-associated gastric cancer (EBVaGC) was one of four classifications of GC, with frequent mutations of PIK3CA, ARID1A, and BCOR, and PD-L1 and PD-L2 amplification; it accounts for up to 10% of its molecular subtypes." (PMID 36353623, 2022).
Lenz microphthalmia (6 papers, 2008 to 2023). "Lenz microphthalmia syndrome (LMS) is an allelic X-linked syndrome correlated to a null mutation of B cell lymphoma (BCL-6) corepressor (BCOR) gene, which is essential in the early embryonic development." (PMID 33491151, 2021). "Mutations in BCOR (MIM 300485) have been seen in families with X-linked recessive inheritance of a phenotype strikingly similar to Lenz microphthalmia syndrome." (PMID 20003547, 2009). "Several studies showed that mutations in the BCL6 corepressor (BCOR) gene located on the X chromosome could be responsible for different diseases such as Lenz microphthalmia syndrome and oculofaciocardiodental (OFCD) in which cardiac defect is one of the main predominate phenotypes." (PMID 34983649, 2022). "Specifically, the MCOPS2 form of Lenz microphthalmia syndrome has been shown to be caused by mutation of the BCL-6 corepressor gene (BCOR), while the genetic etiology of MCOPS1, otherwise commonly called Lenz microphthalmia syndrome, remains unknown." (PMID 33491151, 2021).
rhabdomyosarcoma (6 papers, 2021 to 2026). A rare aggressive malignant mesenchymal neoplasm arising from skeletal muscle. "Genetic testing of the rhabdomyosarcoma revealed a pathogenic c.4102dup (p.R1368fs) germline frameshift variant and a second c.5425G > A (p.G1809R) somatic missense variant in DICER1, as well as a somatic variant in BCOR." (PMID 42311827, 2026). "Also, further studies on the discovered mutations in genes such as CTNNB1, BCOR, FBXW7, and others may provide targets for novel treatments in patients with rhabdomyosarcoma." (PMID 35530877, 2022).
uterine sarcomas (6 papers, 2020 to 2026). "Meanwhile, the diagnosis of BCOR overexpressing uterine sarcomas and high-grade endometrial mesenchymal sarcomas carrying these mutations is suggested by identifying ZC3H7B-BCOR fusion mutations or BCOR-ITD." (PMID 37810911, 2023). "We have recently shown BCOR‐ and YWHAE‐rearranged HGESS to share similar DNA methylation profiles, distinct from LGESS and other high‐grade uterine sarcomas such as ULMS, further supporting the proposed classification." (PMID 32352245, 2020).
aplastic anemia (5 papers, 2019 to 2024). Anemia resulting from bone marrow failure (aplastic or hypoplastic bone marrow). "Individuals with aplastic anemia (who carry oligo-clonal T-cell attacking their BM) presented with increased rate of BCOR and BCORL1 mutations." (PMID 37045808, 2023). "While the BCOR gene and its homolog BCORL1 are implicated in various hematologic malignancies and aplastic anemia, their association with allo-HSCT is rarely reported." (PMID 39408588, 2024). "BCOR/BCORL1 mutations are common in aplastic anemia patients; their presence in LGLL without evidence of any other hematological disorders suggest that they may occur both in myeloid and lymphoid cells." (PMID 36358655, 2022). "Relatively high frequency of BCOR mutations has been reported in aplastic anemia suggesting that these genetic events may confer a selective advantage in the context of aplastic anemia autoimmune environment, although they do not appear to be associated with an increased risk of secondary AML/MDS." (PMID 33159179, 2021).
chronic myelomonocytic leukemia (5 papers, 2019 to 2023). A myelodysplastic/myeloproliferative neoplasm which is characterized by persistent monocytosis, absence of a Philadelphia chromosome and BCR/ABL fusion gene, fewer than 20 percent blasts in the bone marrow and blood, myelodysplasia, and absence of PDGFRA or PDGFRB rearrangement. "BCOR and BCORL1 proteins function as components of PRC1.1, a noncanonical PRC1, and are frequent targets of somatic mutations in AML, sAML, MDS, and chronic myelomonocytic leukemia (CMML)." (PMID 33799787, 2021).
diffuse large B-cell lymphoma (5 papers, 2016 to 2024). "Studies of investigational drug RI-BPI, which inhibits BCL6 by abrogating its interaction with BCOR, show efficacy against diffuse large B-cell lymphomas (DLBCL) with BCL6, representing yet another potential targeted therapy for specific qWT patients." (PMID 27974047, 2016). "Moreover, CBX8 interacted with BCOR in diffuse large B‐cell lymphoma (DLBCL) cells." (PMID 38426219, 2024). "However, frequent mutations in some subunits, such as MGA and BCOR/BCORL1, as well as generally high mutation rates in cancers such as diffuse large B-cell lymphoma (DLBCL) and cholangiocarcinoma of the bile duct (CHOL) point to specific roles for Polycomb subunits in tumor suppression." (PMID 34617019, 2021). "The BCOR K607E mutation was identified in 15 of 47 NK/T cell lymphoma cases (31.9%), 2 of 18 angioimmunoblastic T-cell lymphoma cases (11.1%), 10 of 30 peripheral T-cell lymphoma, not otherwise specified cases (33.3%), and 13 of 42 diffuse large B-cell lymphoma cases (30.9%)." (PMID 33468080, 2021). "BCOR (BCL-6 interacting corepressor) was identified as a corepressor that interacts selectively with the POZ domain of BCL6, a key transcription factor required for the development of germinal center B cells and diffuse large B-cell lymphomas." (PMID 33468080, 2021).
microphthalmia (5 papers, 2008 to 2024). Congenital or developmental anomaly in which the eyeballs are abnormally small. "Further sequence analysis of other genes associated with anophthalmia and microphthalmia such as PAX6, BCOR, OTX2, SIX6, and CHD7 is ongoing in this study cohort to determine mutation associations." (PMID 18385794, 2008). "Congenital cataracts with microphthalmia are highly penetrant in OFCD but less commonly seen in ARS; anterior segment phenotypes including iris synechiae, iris coloboma, and posterior embryotoxon are occasionally reported with BCOR variants." (PMID 37895297, 2023). "BCOR is well recognized with loss-of-function variants linked to X-linked dominant Oculofaciocardiodental (OFCD) syndrome in females, while missense variants are occasionally reported in males, typically with a more severe syndromic microphthalmia phenotype." (PMID 37895297, 2023).
astroblastoma (4 papers, 2020 to 2023). "The group OTHER included for example Astroblastoma, MN-1 altered (n = 1), “CNS tumour with BCOR ITD” (n = 3), “Ewing family tumours” (n = 4) and pineoblastoma (n = 1)." (PMID 36895035, 2023). "Although some features may be more common in one tumor type versus another within the extended NET-MN1 methylation class, HGNET BCOR ex15 ITD, other ependymal or astroblastoma-like tumors, and MAPK astroblastomas, these tumors cannot be reliably distinguished by histology alone." (PMID 36604386, 2023).
bone tumors (4 papers, 2020 to 2025). "The identification of BCOR gene alteration has recently contributed to the definition of new entities in the current WHO (2020) classification of soft-tissue and bone tumors." (PMID 39062853, 2024).
breast carcinoma (4 papers, 2007 to 2024). "None of the other de novo SNVs (i.e., BCL11A, BCOR, and COL1A1) was recurrent in more than one sample nor has been linked to treatment failure in breast cancer, leaving the evolution of resistance unexplained in 12 of 13 replicates." (PMID 38527495, 2024).
endometrial cancer (4 papers, 2020 to 2026). Primary or metastatic malignant neoplasm involving the endometrium (mucous membrane that lines the endometrial cavity). "BCOR mutations are also enriched in salivary gland and endometrial cancers, extending DHODH inhibitors’ potential beyond AML." (PMID 41549155, 2026). "Mutations in the chromatin regulator BCOR have been reported as causative factors for the development of neural and hematological tumors, non-small cell lung cancer, and endometrial carcinoma." (PMID 38256178, 2024).